ZEB1 (zinc finger E-box binding homeobox 1)
Diseases named in the same sentence as ZEB1 in open-access papers (continued):
Sharing a sentence is not in itself a finding about the gene and the disease.
hepatocellular carcinoma (continued). "The predictive role of ZEB1 is also validated in other tumors, such as ovarian carcinoma and hepatocellular carcinoma." (PMID 30976202, 2019). "More importantly, a recent study found knockdown of miR-141-3p upregulated ZEB1 expression and decreased E-cadherin expression in hepatocellular carcinoma cells." (PMID 30755599, 2019). "A previous research indicated that ELF3 promotes epithelial-mesenchymal transition (EMT) by regulating miR-141-3p leading to the enhancement of ZEB1, in hepatocellular carcinoma." (PMID 30429233, 2018). "LncRNA-ATB was shown to promote invasion and metastasis in hepatocellular carcinoma through interactions with members of the miR-200 family and with ZEB1/ZEB2." (PMID 28535802, 2017). "Previous reports have shown that miR-101-3p acted as an oncogenic factor by down-regulating Zinc finger E-box-binding homeobox 1 (ZEB1) in hepatocellular carcinoma and AMPK in triple-negative breast cancer." (PMID 29050268, 2017). "ZFAS1 was reported to promote hepatocellular carcinoma metastasis via sponging miR-150 to activate ZEB1, MMP14, and MMP16." (PMID 28983240, 2017). "LncRNA HULC enhances epithelial-mesenchymal transition to promote tumorigenesis and metastasis of hepatocellular carcinoma via the miR-200a-3p/ZEB1 signaling pathway." (PMID 29050269, 2017). "For example, lncRNA-ATB was over-expressed in hepatocellular carcinoma and up-regulated ZEB1 and ZEB2 by competitively binding the miR-200, thus inducing invasion." (PMID 27564100, 2016). "A previous study demonstrated that high ZEB1 expression in hepatocellular carcinoma was correlated with advanced TNM stage, tumor size, intrahepatic metastasis and vascular invasion." (PMID 23420790, 2013). "The overexpression of ZEB1 has been observed in prostate cancer, gastric cancer, osteosarcoma and hepatocellular carcinoma, suggesting an important role in tumorigenesis." (PMID 23420790, 2013). "Similarly, the migration of human hepatocellular carcinoma cells was impaired in ZEB1 siRNA-treated cells." (PMID 38139138, 2023). "Moreover, USP39 and TRIM26 balanced the expression of ZEB1 to regulate proliferation and metastasis of hepatocellular carcinoma." (PMID 36582601, 2022). "ZEB1 is highly expressed in several tumours, including breast, pancreatic, colorectal, gastric, lung, uterine, hepatocellular carcinoma, prostate and lymphoma cancers." (PMID 36499447, 2022). "EMT transcription factors (Twist, Snail and Zeb-1) were reported as the target genes of Hh signaling in poorly differentiated hepatoma cells, and Hh transactivation endowed the poorly differentiated hepatoma cells with a mesenchymal phenotype and chemo-resistance." (PMID 33440657, 2021). "Furthermore, SNHG6 regulated ZEB1 expression by competitively binding miR-101-3p in hepatocellular carcinoma." (PMID 32321469, 2020). "We, therefore, examined sphere-forming ability of Hepatoma cell lines and upon ZEB1 overexpression." (PMID 31543517, 2019). "Accumulating data indicated that circRNA plays important roles in regulating many biological processes of the tumor, the present study is designated for exploring roles of the circ-ZEB1.33-miR-200a-3p-CDK6 regulating axis in human hepatocellular carcinoma (HCC)." (PMID 30123094, 2018). "LncRNA HULC promoted tumorigenesis via the miR-200a-3p/ZEB1 pathway in hepatocellular carcinoma." (PMID 29970122, 2018). "Similarly, overexpression of miR-139-5p also inhibits epithelial–mesenchymal transition, migration and invasion of hepatocellular carcinoma cells by targeting ZEB1 and ZEB2." (PMID 29618950, 2018). "In addition, USP22 has been reported to regulate ZEB1 ubiquitination to promote the transcription of downstream genes in hepatocellular carcinoma, and we considered whether a similar phenomenon could be observed in OC." (PMID 39530604, 2024). "Moreover, phosphorylated AKT could also induce the transcription of ZEB1 via activating β-catenin in hepatocellular cancer." (PMID 35372504, 2022).
hepatocellular carcinoma (continued). "Moreover, a E3 ligase TRIM26 could promote the degradation of ZEB1 by protein ubiquitination, resulting in the inhibition of cell proliferation and metastasis in hepatocellular carcinoma." (PMID 36512117, 2022). "HOXD9 enhances hepatocellular carcinoma (HCC) cell migration, invasion, and metastasis via the ZEB1 gene expression." (PMID 34572841, 2021). "We previously found that ZEB1 was excessively expressed in hepatocellular carcinoma (HCC) and its high expression was closely correlated with metastasis and recurrence of HCC." (PMID 33897890, 2021). "Circ-ZEB1.33 promotes the proliferation of human hepatocellular carcinoma (HCC) by sponging miR-200a-3p and upregulating the expression of CDK6." (PMID 32005118, 2020). "Further support for such speculations comes from studies that showed increased expression of claudin-1 induced expression of the EMT-regulating transcription factors such as ZEB1 in hepatocellular carcinomas, and claudin-1 can be exploited as a biomarker for liver cancer metastasis." (PMID 32309226, 2020). "In human hepatocellular carcinoma (HCC), the circ-ZEB1.33-miR-200a-3p-CDK6 regulatory axis can regulate HCC cell proliferation." (PMID 32380777, 2020). "While recent research has shown that expression of ZEB-1 in a variety of tumors has a crucial impact on patient survival, there is little information regarding ZEB-1 expression in hepatocellular carcinoma (HCC)." (PMID 24304617, 2013). "In hepatocellular carcinoma, ubiquitin-specific protease 22 (USP22) has been shown to stabilize ZEB1 and thereby upregulate ZEB1-mediated VEGF-A transcription." (PMID 41226394, 2025). "For example, zinc finger E-box-binding homeobox 1 (ZEB1) promotes hepatocellular carcinoma (HCC) proliferation by activating the expression of muscle isoform of phosphofructokinase-1 (PFKM), a key enzyme in the Warburg effect, leading to enhanced glycolysis and elevated lactate levels." (PMID 41152975, 2025). "Of them, lncRNA-ATB upregulated the zing finger E box-binding homeobox (ZEB1 and ZEB2), facilitating the EMT and driving distant metastasis in hepatocellular carcinoma." (PMID 39682098, 2024). "The lncRNA ATB has been reported to increase the expression of ZEB1 and ZEB2 by acting as ceRNA for the miR-200 family, inducing EMT in hepatocellular carcinoma cells." (PMID 36841801, 2023). "Thus, DCAF15 promotes the ubiquitination and degradation of ZEB1 and negatively regulates its protein level, thereby suppressing malignancy of hepatocellular carcinoma (HCC)." (PMID 36805336, 2023). "In hepatocellular carcinoma (HCC), HOXD9 was found to promote epithelial–mesenchymal transition (EMT) by interacting with the promoter of ZEB1." (PMID 37974228, 2023). "Finally, we randomly detected the ZEB1 expression in 20 hepatocellular carcinoma patients by Western blotting, in which 15 patients had higher ZEB1 expression in HCC tissues compared with the paracancerous tissues." (PMID 35589690, 2022). "Mechanistic studies suggest that USP39 stabilizes ZEB1 protein through deubiquitination and activates the development of the EMT pathway and the proliferation and migration of hepatoma cells." (PMID 35875077, 2022). "For instance, lncRNA-ATB competitively binds with the miR-200 family from their targeted ZEB1 and ZEB2 gene, which indirectly contributes to the expression of the oncogene ZEB1/2 and promotes EMT and invasion in hepatocellular carcinoma." (PMID 34660788, 2021). "In hepatocellular carcinoma, ELF3 promotes epithelial-mesenchymal transition by protecting ZEB1 from miR-141-3p-mediated silencing." (PMID 33070167, 2020). "lncRNA-ATB is a classic example, which competitively binds miR-200s and upregulates miR-200s targets ZEB1 and ZEB2 in hepatocellular carcinoma." (PMID 34094894, 2020).
hepatocellular carcinoma (continued). "Zinc finger E-box binding homeobox 1 (ZEB1), a protein that induces EMT in cancer cells, had already been established as a direct target of miR-431 in hepatocellular carcinoma." (PMID 32781574, 2020). "For instance, lncRNA ZFAS1 activated the expression of ZEB1, MMP-14 and MMP-16 to promote tumor growth and metastasis by sponging miR-150 in hepatocellular carcinoma." (PMID 31827393, 2019). "Initially we analysed ZEB1, ZEB2, E-cadherin and vimentin expression in eight Hepatoma-derived cell lines." (PMID 31543517, 2019). "For example, ATB lncRNA blocked miR-200 family by binding to its targets and upregulated ZEB1 and ZEB2, thereby inducing EMT and invasion in hepatocellular carcinoma." (PMID 30181715, 2018). "For example, LncRNA-ATB was shown to induce hepatocellular carcinoma EMT and invasion by competitively binding to and inhibiting miR-200 family members and then upregulating ZEB1 and ZEB2." (PMID 28095858, 2017). "In hepatocellular carcinoma, ZFAS1 functions as an oncogene in HCC progression by binding miR-150, which adsorbs ZEB1, MMP14 and MMP16 expression, and abrogating the tumor-suppressive." (PMID 29262629, 2017). "Herein, we investigated how Snail upregulated transcription of ZEB1 and MMP9 induced by the tumor promoter 12-O-tetradecanoyl-phorbol 13-acetate (TPA) in hepatoma cell HepG2." (PMID 29259250, 2017). "Another lncRNA, the lncRNA-activated by TGF-b (lncRNA-ATB) could promote hepatocellular carcinoma (HCC) cell invasion by competitively binding the miR-200 family, upregulating ZEB1 and ZEB2, and then inducing EMT." (PMID 27628540, 2016). "In Hepatocellular Carcinoma, lncRNA-activated by TGF-β (lncRNA-ATB) upregulated ZEB1 and ZEB2 by competitively binding the miR-200 family and then induced EMT and invasion." (PMID 27613832, 2016). "Cellular experiments confirmed that increased 14-3-3ε expression induces hepatocellular carcinoma cell migration and promotes epithelial-mesenchymal transition (EMT) by inducing Zeb-1 and Snail expression." (PMID 24926661, 2014). "Consequently, elevated glucose concentrations may enhance cellular susceptibility to ferroptosis by facilitating the O-GlcNAcylation of YAP1 and ZEB1 in hepatocellular carcinoma (HCC) and pancreatic cancer cells." (PMID 41350524, 2025). "A recent study emphasized the interaction between Dio3os and the NONO protein, which impedes the NONO-mediated nuclear export of ZEB1 mRNA, a crucial pathway in attenuating hepatocellular carcinoma progression." (PMID 41235096, 2025). "More recently, METTL13 has been shown as a crucial mediator of HN1L (hematological and neurological expressed 1-like) in modulating hepatocellular carcinoma (HCC) cell growth and metastasis via co-activating TCF3 (transcription factor 3) and ZEB1 (zinc finger E-box binding homeobox 1) expression." (PMID 35925508, 2023). "Circ-ZEB1 promotes phosphatidylinositol-4,5-bisphosphate 3-kinase catalytic subunit alpha (PIK3CA) expression by sponging miR-199a-3p, which affects the proliferation and apoptosis of hepatocellular carcinoma." (PMID 36609391, 2023). "We found that JPHYD could inhibit the proliferation, invasion, and migration of hepatocellular carcinoma cells and JPHYD decreased the level of N-cadherin, Snail, Vimentin, Smad3, and Zeb1 and increased E-cadherin and Smad7 proteins." (PMID 35518787, 2022). "To explore whether ZEB1 could enhance glycolysis in HCC, we knocked down ZEB1 by short hairpin RNA (shRNA) in MHCC-97H and HCC-LM3 cells (both are hepatocellular carcinoma cell lines with high metastasis potential) and performed glucose uptake and lactate production assays." (PMID 33897890, 2021). "In addition to COL1A1 and DDR1 knockdown, ZEB1 suppression significantly decreased SNU449 cell invasiveness, implying involvement of the COL1A1/DDR1/ZEB1 axis in hepatoma cell invasiveness." (PMID 34772924, 2021).
hepatocellular carcinoma (continued). "In agreement with findings from this study, miR-941 was shown to act as a tumor suppressor by suppressing cancer growth and migration of gastric and hepatoma cells via direct target of EMT inducers SNAIL1, ZEB1 and ZEB2 and promotes E-cadherin expression in the cancer cells." (PMID 33374139, 2020). "For instance, the SE-induced seRNA HCCL5 promotes hepatocellular carcinoma (HCC) cells viability, migration and epithelial-to-mesenchymal transition (EMT) by upregulating Snail, Slug, ZEB1, and Twist1." (PMID 35461306, 2022). "It was shown to be downregulated and might function as a tumor suppressor by targeting Myc, FSCN1 in gastric cancer, ZEB1 in oral squamous cell carcinoma, CRKL in hepatocellular carcinoma, TLN1 in nasopharyngeal carcinoma, AKT1 in melanoma, or BCL2 and SP1 in esophageal carcinomas." (PMID 33414893, 2020). "High ZEB1 expression is observed in hepatocellular carcinoma patients with or without cirrhosis." (PMID 33058500, 2020). "However, ZEB1 did not predict poor OS for patients with esophageal squamous cell carcinoma (pooled HR: 1.338, 95% CI: 0.965-1.854, p=0.081) and hepatocellular carcinoma (pooled HR: 1.364, 95% CI: 0.989-1.881, p=0.059)." (PMID 28416756, 2017). "Besides, MALAT1 could bind miR-200s to regulate ZEB2 in ccRCC, while LncRNA-ATB could regulate ZEB1 and ZEB2 by competitively binding the miR-200s to control EMT and invasion in hepatoma cells." (PMID 29156724, 2017). "Furthermore, both patients with ZEB1+ tumors exhibit no clinically reported signs of cirrhosis, which is especially compelling in patient HCC-5 given that hepatocellular carcinoma commonly emerges in livers previously affected by damage or deterioration." (PMID 40830586, 2025). "Transcript and protein abundance of ZEB1 and regulators of mitochondrial fission and fusion were quantified in patient-matched tumor and non-tumor tissues of hepatocellular carcinoma (HCC) and cholangiocellular adenocarcinoma (CCA) from our clinic and common liver cancer cell lines." (PMID 40830586, 2025). "Similar results had been obtained in hepatocellular carcinoma (HCC) and triple-negative breast cancer (TNBC) models in which FOXM1b dysregulation promoted the expression of mesenchymal markers, such as N-cadherin, Snail, and Zeb1, as well as the repression of the epithelial marker E-cadherin." (PMID 37174744, 2023).
prostate carcinoma (153 papers, 2010 to 2025). A carcinoma that arises from epithelial cells of the prostate gland. "The regulation of epithelial‐mesenchymal transition (EMT) and cancer stem cell properties were found to be closely linked to ZEB1‐mediated VM formation in prostate cancer cells." (PMID 36708044, 2023). "ZEB1 (zinc finger E-box binding homeobox 1) has frequently been associated with cancer in general, and prostate cancer in particular." (PMID 32252623, 2020). "In a previous study, miR-301a was found to induce EMT in prostate cancer cells through inhibition of p63, which caused the release of ZEB1/2 in a miRNA-mediated inhibition and induction EMT." (PMID 32252322, 2020). "The underlying molecular events of ZEB1‐induced vasculogenic mimicry formation in prostate cancer were then explored." (PMID 29754422, 2018). "One such pathway is the SNAI1/2, which regulate ZEB1/2 expression and have been implicated in prostate cancer." (PMID 21747944, 2011). "The zinc-finger E-box binding homeobox proteins 1 and 2 (ZEB1/2) have also been implicated in EMT; in vitro prostate cancer models revealed that ZEB1 binds to the E-cadherin promoter and recruits the histone deacetylase Sirtuin-1, resulting in histone deacetylation and repression of E-cadherin." (PMID 39095874, 2024). "Also, ZEB1 expression was associated with prostate cancer (PCa) progression and metastasis, while Twist1 plus ZEB2 expression was related to early disease recurrence in HCC." (PMID 28590039, 2017). "Because it is induced by estrogen and progesterone and is high in prostate cancer, we investigated whether tcf8, which encodes ZEB1, is regulated by androgen." (PMID 22190929, 2011). "Additionally, TSA also led to prostate cancer aggressiveness via induction of epithelial-to-mesenchymal transition phenotype which associated with increased expression of transcription factors ZEB1, ZEB2 and Slug, and mesenchymal markers such as vimentin, N-cadherin and fibronectin." (PMID 28785170, 2017). "Only two publications have shown a role for ETV4 in EMT via ZEB1 regulation in breast and prostate cancers." (PMID 40275610, 2025). "Our findings corroborate with previous reports demonstrating ZEB1-mediated regulation of N-cadherin in prostate cancer cells and vimentin in melanoma." (PMID 40664642, 2025). "A recent study showed that DAPK1 regulates cancer stem cells in prostate cancer by interacting with the zinc finger E-box-binding homeobox-1 (ZEB1) to inhibit the Hippo/YAP signaling pathway in PCa-CD133(+) cells." (PMID 39057063, 2024). "In prostate cancer, the transcription factor Zeb1 binds to the E-box in the SDC1 promoter, suppressing its expression." (PMID 39728992, 2024). "Hypoxia promotes the aggressiveness of prostate cancer by upregulating the expression of the EMT activator Zeb1 and SK3 channel." (PMID 37384143, 2023). "MiR-200a (osteosarcoma), miR-200b (gastric cancer, oral squamous cell carcinoma, osteosarcoma), miR-200c (prostate cancer), and miR-429 (cervical cancer, osteosarcoma, thyroid cancer) all target ZEB1/2 in different cancers." (PMID 37238740, 2023). "For example, in induced pluripotent stem cells (iPSC) and prostate cancer cells, mesenchymal genes, such as ZEB1, ZEB2, CDH2, TWIST and SNAI1/2, are enriched with EZH2 binding, but not epithelial genes such as CDH1 or SNAI3." (PMID 37175580, 2023). "Recently, it was reported that miR-182 overexpression upregulated EMT-related genes, such as N-cadherin, vimentin, and ZEB1, but downregulated E-cadherin expression in prostate cancer cells." (PMID 36293154, 2022). "Hypoxia-induced upregulation of SK3 together with the EMT transcription factor Zeb1 in prostate cancer cells is promoted by the anti-androgen Enzalutamide, used for the treatment of castration-resistant prostate cancer." (PMID 36612099, 2022).